MEMO1 (mediator of cell motility 1)
Diseases named in the same sentence as MEMO1 in open-access papers (continued):
Sharing a sentence is not in itself a finding about the gene and the disease.
colorectal cancer (3 papers, 2020 to 2024). A primary or metastatic malignant neoplasm that affects the colon or rectum. "In colon cancer, Ahr/ARNT activity was mediated by expression of Memo-1, a gene implicated in colorectal carcinoma (CRC) migration, and Memo-1 depletion led to decreased CRC cell migration and invasion." (PMID 38339226, 2024). "In colorectal cancer cells Memo1 promoter activity is increased in response to the transcription factors Aryl hydrocarbon receptor/ Aryl hydrocarbon receptor nuclear‐translocator complex, indicating some intestinal disease relevance." (PMID 32291966, 2020). "In support of the biological significance of cancer-associated upregulated MEMO1 expression, were the observations that elevated MEMO1 levels correlated with a more aggressive disease prognosis and significantly reduced patient survival—in both breast and colorectal cancer cohorts." (PMID 33172038, 2020). "Indeed, upregulation of MEMO1 has now been observed in both breast and colorectal cancers." (PMID 33172038, 2020). "Likewise, examination of mRNA expression levels in biopsied colorectal cancer tissue (n = 30), revealed ~60% of samples had elevated MEMO1 (along with HER2) expression, relative to normal colorectal tissue, a feature also observed at the protein level by anti-MEMO1 immunostaining." (PMID 33172038, 2020).
alopecia (2 papers, 2018 to 2020). Hair loss usually from the scalp. "For example, MEMO1 postnatal mutants, relative to controls, display weight loss, a decrease in subcutaneous fat, small stature, kyphosis, loss of spermatozoa, graying hair, alopecia and a shortened lifespan." (PMID 33172038, 2020). "In addition to these findings, Memo cKO mice showed hypersensitivity to insulin, and signs of premature aging: Memo1 deletion caused alopecia, hair graying, kyphosis, infertility, atrophy of subcutaneous fat, and Memo cKO mice have a shortened life span." (PMID 30038585, 2018). "Likewise, some patients in the DECIPHER database with CNVs around or including MEMO1 are reported to have sparse and thin eyebrows, sparse eyelashes, alopecia, along with additional skin abnormalities (e.g., pigmentation)." (PMID 33172038, 2020).
autism (2 papers, 2020 to 2022). Persistent deficits in social interaction and communication and interaction as well as a markedly restricted repertoire of activity and interest as well as repetitive patterns of behavior. "MEMO1 mutations and the resulting cortical abnormalities may increase the risk of autism." (PMID 36385761, 2022).
chronic kidney disease (2 papers, 2020 to 2023). Impairment of the renal function secondary to chronic kidney damage persisting for three or more months. "Loss of the mediator Of cell motility 1 (Memo1) in mice caused kidney disease and a bone disease with diminished osteoblast and osteoclast biomarkers in serum, resembling alterations occurring in adynamic bone disease in humans with chronic kidney disease or in Klotho‐deficient mice." (PMID 36967231, 2023). "Here, we set out to describe the role of FGFR modulator Memo1 in the osteoblast and in bone‐derived FGF23 expression under experimental AKI, based on reports that FGFR‐Klotho signaling is required for FGF23 expression during chronic kidney disease in mice." (PMID 36967231, 2023). "The comparability of the two models is however limited by the chronic kidney disease (CKD) that develops in Memo1 cKO but not in Memo1 kKO mice which have normal serum creatinine levels." (PMID 32706793, 2020).
kidney failure (2 papers, 2023). An acute or chronic condition that is characterized by the inability of the kidneys to adequately filter the blood. "Moreover, four to eight weeks after undergoing Memo1 exon 2 excision recombination, Memo cKO animals developed kidney failure, elevated serum concentrations of FGF23 and calcium, and a bone and mineral disease." (PMID 36434320, 2023).
lung carcinoma (2 papers, 2020 to 2022). "Finally, are there certain tumor subtypes (e.g., subtypes of breast, colorectal, pancreatic and lung cancer) that MEMO1 plays a more prominent role in and how might Circ-MEMO1 RNA contribute to these various pathogenic subtypes?" (PMID 33172038, 2020). "Circ_GLG1/miR-622, circFNTA/miR-370-3p and circ-MEMO1/miR-101-3p axes have been shown to regulate expression of KRAS in colorectal, bladder and lung cancer cells." (PMID 35139853, 2022).
non-small cell lung carcinoma (2 papers, 2022 to 2024). A group of at least three distinct histological types of lung cancer, including non-small cell squamous cell carcinoma, adenocarcinoma, and large cell carcinoma. "These regulatory networks encompassing circ_0048856-miR-1287-5p, circ-MEMO1-miR-101-3p-KRAS, and circ_00007355-miR-345-5p-ADAM19 play a role of detection of non-small cell lung cancer." (PMID 39021878, 2024).
pancreatic adenocarcinoma (2 papers, 2010 to 2020). "Further, although requiring validation with additional samples, MEMO1 expression levels were also found elevated (3×) in a primary pancreatic adenocarcinoma, relative to control pancreatic cells, likely as a result of MEMO1 locus amplification (11×)." (PMID 33172038, 2020). "Numerous genes were overexpressed, some of which have previously been implicated in pancreatic adenocarcinoma (GATA6, IGFBP3, IGFBP6), while others were detected for the first time (MEMO1, RIOK3)." (PMID 20553613, 2010). "For some of these genes putative roles in pancreatic adenocarcinoma progression have been identified, as RIOK3 and MEMO1 or in tumor angiogenesis such as TBK1." (PMID 20553613, 2010).
triple-negative breast carcinoma (2 papers, 2024 to 2025). An invasive breast carcinoma which is negative for expression of estrogen receptor (ER), progesterone receptor (PR), and human epidermal growth factor receptor 2 (HER2). "Metabolite levels were measured in triple-negative breast cancer cell lines with high, low and no MEMO1 expression." (PMID 40278406, 2025). "To experimentally investigate the link between MEMO1 and the TCA activity suggested by our bioinformatic analyses, we employed a targeted metabolomics approach to measure key TCA metabolites in the MDA-MB-231 triple-negative breast cancer cell line, which exhibits high MEMO1 expression." (PMID 40278406, 2025).
breast tumors (1 paper, 2024). "In cancer context, MEMO1 supports the ability of breast tumor cells to invade surrounding tissues, leading to metastasis." (PMID 38640016, 2024).
ductal carcinoma in situ (1 paper, 2020). "miRNA targeting of MEMO1 is also likely involved, as has been shown in the context of ductal carcinoma in situ (also in normal embryonic development)." (PMID 33172038, 2020).
dwarfism (1 paper, 2023). "The postnatally-inducible ubiquitous deletion of Memo1 exon 2 (Memo cKO) using Cre-lox techniques resulted in a mouse phenotype of premature aging with dwarfism, alopecia, hair graying, loss of subcutaneous fat, hypogonadism, and abnormal gait." (PMID 36434320, 2023).
gastric cancer (1 paper, 2022). A primary or metastatic malignant neoplasm involving the stomach. "lncRNA cancer susceptibility 20 (CASC20) was reported to serve as a tumor promoter by promoting the metastasis of human gastric cancer cells by the miR-143-5p/MEMO1 molecular axis." (PMID 36105083, 2022).
Iron Deficiency (1 paper, 2025). "In the context of MEMO1’s role in iron regulation, this rise in glutamate may represent an adaptive response to oxidative stress induced by iron deficiency." (PMID 40278406, 2025). "This suggests that iron deficiency exacerbates fumarate accumulation in the absence of MEMO1." (PMID 40278406, 2025).
melanoma (1 paper, 2024). A malignant, usually aggressive tumor composed of atypical, neoplastic melanocytes. "By comparison, MEMO1 knockdown or knockout in melanoma cells decreased only the expression level of TFR2, the effect on SLC25A28 knockdown being difficult to interpret." (PMID 38640016, 2024). "A similar MEMO1-dependent growth activation pattern was also observed in melanoma cell lines." (PMID 38640016, 2024). "As expected, no strong motility or proliferation rate dependence on MEMO1 expression level was observed in the melanoma cells." (PMID 38640016, 2024). "Thus, melanoma serves as a useful benchmark for a cancer, where MEMO1 overexpression is not required to support malignant transformation." (PMID 38640016, 2024).
Parkinson disease (1 paper, 2020). A progressive degenerative disorder of the central nervous system characterized by loss of dopamine producing neurons in the substantia nigra and the presence of Lewy bodies in the substantia nigra and locus coeruleus. "Further, MEMO1 was identified, using a meta-analysis of previous Parkinson’s Disease GWAS studies, to be one of only 14 genes that was associated (suggestive association, p = 2.34 × 10−5 with Parkinson’s Disease risk and was also mis-regulated in the proteomic analysis." (PMID 33172038, 2020). "Further extending MEMO1′s potential role in neurological pathology, MEMO1 was found to have a connection—via a combined proteomic and GWAS analysis—in the neuroinflammatory response of Parkinson’s Disease." (PMID 33172038, 2020). "Again, while more work is required to test the functional significance of these findings—specifically in the context of Parkinson’s Disease etiology—they suggest MEMO1′s role in neuropathology may be broader than currently appreciated." (PMID 33172038, 2020).
Stroke (1 paper, 2023). Sudden impairment of blood flow to a part of the brain due to occlusion or rupture of an artery to the brain. "Circ-Memo1, which has been shown to be a potential therapeutic target for cancer, was upregulated in the peripheral blood of stroke patients in a recent study." (PMID 38203348, 2023). "Knocking out circ-Memo1 in hypoxia/reoxygenation(H/R)-treated HBMVECs cells increased the expression level of miR-17–5p and decreased the activity of SOS1, reducing oxidative stress and cell damage after stroke and improving cell viability." (PMID 38203348, 2023).
tumor (16 papers, 2004 to 2026). "Relative to ‘control’ cells (targeted with a control shRNA), MEMO1 knockdown cells showed decreased metastases to the lung, associated with a decreased propensity for tumor intravasation and lung extravasation." (PMID 33172038, 2020). "indicate that miR‐219a‐1 is downregulated in CRC and functions as a tumor suppressor by inhibiting cancer cell proliferation, invasion, and migration through targeting MEMO1." (PMID 40620190, 2025). "EMT-related proteins [mediator of ErbB2-driven cell motility 1 (MEMO1), E-cadherin, fibronectin, vimentin, and vinculin] were quantified by Western blotting in tumor and adjacent normal mucosa." (PMID 40507970, 2025). "Further research is needed to fully elucidate how MEMO1 orchestrates these metabolic adaptations in light of its iron-binding activity and the impact of these adaptations on tumor progression." (PMID 40278406, 2025). "It is well understood that E7 induces the proteasomal degradation of various tumor suppressors, such as pRb and mediator of cell motility 1, by interacting with the CUL2 ubiquitin ligase complex." (PMID 38226814, 2024). "MEMO1 promotes tumor cell migration and metastasis via EMT-related pathways, which are obtained from BC cells." (PMID 35782923, 2022). "In sum, while the bulk of MEMO1 knowledge has emerged from studies relevant to cancer and tumor biology, several open questions remain to be resolved." (PMID 33172038, 2020). "In a similar vein, it will be important to identify the exact mechanisms by which MEMO1 expression is upregulated during tumor progression." (PMID 33172038, 2020). "There were 45 NSCLC patients with higher expression of circ-MEMO1 in tumor tissues than that in normal tissues." (PMID 33005174, 2020). "The results of animal experiment suggested that circ-MEMO1 silencing restrained the tumor growth of NSCLC in vivo." (PMID 33005174, 2020). "To explore the function of circ-MEMO1 in the NSCLC tumor growth in vivo, we injected A549 cells stably expressing sh-NC or sh-circ-MEMO1 into the nude mice." (PMID 33005174, 2020). "Examination of NSCLC patients (n = 52) revealed that ~87% of them had elevated Circ-MEMO1 levels in tumor tissue relative to adjacent ‘normal’ tissue." (PMID 33172038, 2020). "Another intracellular Cu-dependent protein is mediator of cell motility 1 (MEMO1), a redox enzyme that has been reported to facilitate tumor cell migration and metastasis through several molecular mechanisms." (PMID 28425924, 2017). "The elevated citrate levels in MEMO1-KO cells may indicate a metabolic adaptation that favors oxidative phosphorylation and lipid biosynthesis, both of which are essential for tumor growth and survival." (PMID 40278406, 2025). "A major outcome of MEMO1-mediated signaling is cell migration, which is an essential event during organismal development, adult homeostasis (e.g., cellular immunity, wound healing, etc.), and pathogenesis (e.g., tumor metastasis)." (PMID 36603019, 2023). "In vivo tumor growth assay was conducted to assess the effect of circ-MEMO1 in vivo." (PMID 33005174, 2020). "In addition, circ-MEMO1 was down-regulated in tumor tissues in a total of seven NSCLC patients compared with adjacent normal tissues." (PMID 33005174, 2020). "One prediction from these studies (along with in vitro studies) was that MEMO1 expression could be altered in patient-derived tumor samples." (PMID 33172038, 2020). "Circ-MEMO1 silencing suppressed the NSCLC tumor growth in vivo." (PMID 33005174, 2020). "Furthermore, miR-101-3p level was higher in tumor tissues with the silencing of circ-MEMO1 compared with sh-NC group." (PMID 33005174, 2020). "For example, is MEMO1 a ‘driver’ or ‘passenger’ gene in tumor progression?" (PMID 33172038, 2020). "Similarly, WWP1, SDC1 (syndecan 1), EZH2, CCND1, ADAM9 and MEMO1 have oncogenic activities and are targeted by the potentially tumor suppressor miRNA miR-195, miR-10b, let-7c, miR-17 and miR-125b." (PMID 21375733, 2011).
tumor (continued). "The tumor-derived exosomes could take part in the NSCLC development, such as circRNA ARHGAP10, circRNA MEMO1, and hsa_circ_0002130." (PMID 35582196, 2022). "Through an unbiased screen, MEMO1 was shown to interact with phospho-Tyrosine (pY) 1227 on the C-terminus of ERBB2 after ligand (Heregulin, HRG) stimulation—a residue shown to be important for tumor cell migration." (PMID 33172038, 2020). "Relative to ‘control’ tumor cells (targeted with a control shRNA), knockdown of MEMO1 resulted in absent or reduced tumor growth." (PMID 33172038, 2020). "High expression of circ-MEMO1 was correlated with the advanced clinical stage and positive lymph node metastasis but not that of age, gender, and tumor size." (PMID 33005174, 2020). "Overexpression of the putative tumor suppressor miR-125b, which is underexpressed in DCIS, repressed the expression of MEMO1, which is required for ErbB2-driven cell motility (also a target of miR-125b), and NRIP1/RIP140, which modulates the transcriptional activity of the estrogen receptor." (PMID 21375733, 2011).
cancer (12 papers, 2017 to 2025). A tumor composed of atypical neoplastic, often pleomorphic cells that invade other tissues. "Given the enrichment of the TCA-cycle related genes in these datasets, it is likely that MEMO1 role in iron homeostasis is linked to metabolic adaptations in the TCA cycle in cancer cells." (PMID 40278406, 2025). "Here, we investigated copper binding to Memo1, an oncogenic protein linked to cancer." (PMID 36067318, 2022). "Taken together, these findings suggest that MEMO1 has a specific function in regulating iron levels within the mitochondria, beyond its broader role in overall iron homeostasis in cancer cells." (PMID 40278406, 2025). "In conclusion, our results indicate that MEMO1 contributes to the modulation of cancer cell metabolism in response to iron availability." (PMID 40278406, 2025). "MEMO1, a modulator of cancer metastasis, has been shown to bind iron and regulate iron homeostasis in the cells." (PMID 40278406, 2025). "To better understand the role of MEMO1 in mitochondrial function we have conducted a genome-wide analysis of MEMO1 genetic interactions using gene essentiality data contained in several databases of single-gene knockouts and knockdowns in cancer cells." (PMID 40278406, 2025). "A genome-wide in silico analysis of publicly available gene essentiality data from 1028 cancer cell lines has identified numerous proteins involved in iron metabolism that display statistically significant genetic interactions (GIs) with MEMO1." (PMID 40278406, 2025). "We called a given gene to exhibit GI with MEMO1 if this gene was found to become essential only in cancer cells that either overexpress or downregulate MEMO1." (PMID 38640016, 2024). "PLOD1 is an iron-containing enzyme, which participates in the collagen assembly and in the regulation of collagen synthesis and extracellular matrix remodeling, consistent with the established role of MEMO1 in cancer cell tissue invasion and metastasis." (PMID 38640016, 2024). "(A) Gene essentiality score distribution for the selected genes in the high- and low-MEMO1 expressing groups in multiple cancer cell lines as shown by the database analysis." (PMID 38640016, 2024). "In summary, our work has revealed that MEMO1 is an iron-binding protein that regulates iron homeostasis in cancer cells." (PMID 38640016, 2024). "To better understand the function of MEMO1 in cancer cells, we analyzed genetic interactions of MEMO1 using gene essentiality data from 1028 cancer cell lines and found multiple iron-related genes exhibiting genetic relationships with MEMO1." (PMID 38640016, 2024). "The mediator of ERBB2-driven cell motility 1 (Memo1) is a protein connected to cancer progression that has been proposed as a cancer drug target (13, –15)." (PMID 36067318, 2022). "The protein mediator of ERBB2-driven cell motility 1 (Memo1) is connected to many signaling pathways that play key roles in cancer." (PMID 36067318, 2022). "Memo1 was recently postulated to bind copper (Cu) ions and thereby promote the generation of reactive oxygen species (ROS) in cancer cells." (PMID 36067318, 2022). "As Memo1 is a putative target for the treatment of cancer, it is of importance to identify its binding partners (e.g., metal ions) and the functional consequences of such interactions." (PMID 36067318, 2022). "Our results raise several questions about the role of Memo1 in cancer cells: how are two Cu(I) ions coordinated in Memo1?" (PMID 36067318, 2022). "While MEMO1′s experimental ‘history’ began with a link to cancer, new studies continue to solidify this link in a variety of new cancer contexts." (PMID 33172038, 2020). "It is interesting to note, however, that databases of MEMO1′s cell essentiality are often near the level of significance—with a variety of cell lines (e.g., 236 of 777 cancer cell lines, depmap portal) in which viability is dependent on MEMO1 function." (PMID 33172038, 2020).